VSIR (V-set immunoregulatory receptor)
Diseases named in the same sentence as VSIR in open-access papers (continued):
Sharing a sentence is not in itself a finding about the gene and the disease.
cancer (222 papers, 2016 to 2026). A tumor composed of atypical neoplastic, often pleomorphic cells that invade other tissues. "Both B7-H3 and VSIR are immunoregulatory proteins, which are overexpressed in various cancers and associated with poor prognosis." (PMID 33819918, 2021). "Finally, we explored the association of VSIR expression with prognosis in other blood cancers and cancer types." (PMID 36394080, 2023). "VSIR was found to co-expression with cancer cells and various inflammatory cells, such as T cells, B cells, regulatory T cells (Tregs), macrophages, M2 macrophages, cancer-associated fibroblasts (CAFs), monocytes, microglial cells, and astrocytes." (PMID 35493077, 2022). "In the TCGA database, VSIR mRNA levels were higher in AML patients compared to all 30 other human cancer types, and VISTA protein is detectable in most AML samples." (PMID 40175626, 2025). "Consistent with YAP activation by EMT, MDA-MB-231 mesenchymal cancer cells exhibited high basal expression of VSIR proteins." (PMID 40940864, 2025). "YAP activation or VSIR overexpression increased cancer cells’ resistance to T cell-mediated destruction." (PMID 40940864, 2025). "In the present study, we evaluated the expression of the immune checkpoints CD276, CD44, TNFRSF14, and VSIR across a range of cancer tissues." (PMID 40727469, 2025). "ReMap ChIP-seq data confirmed the strong binding of TEAD1/4 and YAP at the promoter and intron 1 of VSIR, as well as at the promoter of PD-L2 in a variety of cancer cells." (PMID 40940864, 2025). "Specifically, several immune checkpoints including TNFRSF18, TNFRSF4, VSIR, LGALS9, HAVCR2, and TNFRSF14 are significantly associated with RARA-AS1 in more than 10 types of cancer." (PMID 37833349, 2023). "V‐domain Ig suppressor of T cell activation (VSIR) is one of these immune checkpoint genes and has been investigated extensively in recent years due to its conflicting roles in cancer immunity." (PMID 36394080, 2023). "VSIR expression was positively related to various infiltrated inflammatory cells in most cancer types." (PMID 35493077, 2022). "Multiple cell types can express VSIR, such as cancer cells, neutrophils, monocytes, macrophages, dendritic cells (D.C.s), and T cells in humans and mice." (PMID 35493077, 2022). "It was found that VSIR maintains a close relationship with these inflammatory cells in most cancers, especially with T cells, CAFs, macrophages, M2 macrophages, Tregs, neutrophils, monocytes, microglial cells, and astrocytes." (PMID 35493077, 2022). "According to the correlation analysis between SRSF3 and immune checkpoint gene expression, it can be found that SRSF3 is closely related to TNFSF14, TNFRSF14, TNFRSF25, CD276, NRP1, VSIR in a variety of malignant tumors (P <0.05)." (PMID 35494088, 2022). "It should be noted that in cancer types with high infiltration of M2 macrophages and high expression of VSIR, patients with the corresponding cancers were associated with decreased survival, which might also partly explain the observation that VSIR behaves similarly in some cancers." (PMID 35493077, 2022). "In this study, two immune checkpoints (B7-H3 and VSIR), which were previously reported to be attractive targets for immnuotherapy in different cancers, were upregulated in high-risk patients." (PMID 35465325, 2022). "Results indicated that VSIR levels significantly positively correlated with these immune checkpoints in many cancers, especially in BRCA, COAD, LIHC, SKCM, PRAD, TGCT, and UVM (P<0.05)." (PMID 35493077, 2022). "VSIR was found to co-expression with CD163+ cells in these cancers, including GBM, LSCC, BLCA, CESC, PSCC, and TGCT." (PMID 35493077, 2022). "Moreover, YAP activation directly induced transcription of B7 family immune checkpoint proteins VSIR (VISTA) and PD-L2, and rendered cancer cells resistant to effector CD8 T cells." (PMID 40940864, 2025).
cancer (continued). "Inclusion of VSIR blockade in combinatorial immunotherapies may help overcome resistance to current ICIs in YAP-activated cancer cells." (PMID 40940864, 2025). "We further determined if high VSIR expression in certain cancer cells was driven by endogenous YAP." (PMID 40940864, 2025). "The V-set immunoregulatory receptor (VSIR) is a recently identified novel member of the B7 immune checkpoint (IC) family of immunoregulatory genes and has emerged as a promising target for combined cancer immunotherapy." (PMID 41417109, 2025). "Overall, this supports the consensus that VSIR plays a multifaceted role in cancer immunity across different cancers and may have co‐inhibitory or stimulatory roles in the immune response." (PMID 36394080, 2023). "Thus, the VSIR signaling pathway has increasingly become a promising immunotherapy target in anti-cancer treatment in recent years." (PMID 35493077, 2022). "We found that VSIR levels are positively related to immune score, estimate score, and stromal score in almost all cancers." (PMID 35493077, 2022). "VSIR has been demonstrated to express in hematopoietic cells initially and VSIR could be a target of the cancer immunotherapy." (PMID 36098688, 2022). "Furthermore, in multiple cancer types, CD93 expression positively correlates with the expression of various immune checkpoint molecules, including CD86, leukocyte-associated immunoglobulin-like receptor 1 (LAIR1), V-set immunoregulatory receptor (VSIR), and neuropilin 1 (NRP1)." (PMID 40943530, 2025). "This indicates that VSIR expression is prominent in both cancer cells (CCLE) and the cancer microenvironment (TCGA), including immune cells that have infiltrated into the bone marrow." (PMID 36394080, 2023). "Using the TCGA (The Cancer Genome Atlas) and CCLE (Cancer Cell Line Encyclopedia) datasets, we first investigate the expression levels of VSIR in AML compared to other cancers and other immune checkpoint targets." (PMID 36394080, 2023). "Our analysis in this study indicates that VSIR has the highest expression levels in AML compared to other cancer types; and in AML VSIR has the highest expression than the other immune checkpoint genes." (PMID 36394080, 2023). "CD276 showed the highest positive correlations with JMJD8 in 15 cancers, followed by LGALS9, VSIR, and TNFRSF4." (PMID 35898493, 2022). "Data showed that the many immune checkpoints positively correlate with CD93 expression in many cancers, particularly NRP1, LAIR1, VSIR, and CD86." (PMID 36389798, 2022). "In this study, we clarified the correlation between VSIR expression and infiltrated immune cells in the TME among these cancers through public databases, single-cell sequencing analysis, and multiplex immunofluorescence staining." (PMID 35493077, 2022). "In contrast, VSIR, HAVCR2, and CD86 were negatively correlated with METTL3 expression in several cancer types." (PMID 36614956, 2022). "We next validated whether expression of VSIR and PD-L2 correlated with YAP activity in human cancer cell lines." (PMID 40940864, 2025). "Also, the immune checkpoint VSIR was expressed on some T cell subpopulations of MBC samples and interacted with the cancer cells via TNF." (PMID 37696831, 2023). "VSIR is a negative immune checkpoint regulator, and as such, with promising use in cancer treatment." (PMID 37192378, 2023). "Notably, VSIR, LGALS9, and TNFRSF14 are highly correlated with RARA-AS1 in 16 types of cancer, indicating their potential as therapeutic targets." (PMID 37833349, 2023). "While CD276, ENTPD1, IDO1, LGALS9, and VSIR were commonly detected in the Stereo‐seq samples, only IDO1 and LGALS9 seemed to have higher and wider expression in the CSCC samples than in the non‐cancer samples." (PMID 35986392, 2022). "In addition, NRP1, CD276, and VSIR showed obvious positive correlation with SLC7A11 expression in most cancers, although the drugs targeted at these checkpoints have not been applied in clinic." (PMID 34938318, 2021).
cancer (continued). "Importantly, for all cell types, VSIR expression increases when the cell develops AML, with monocytes having the highest VSIR expression with or without cancer." (PMID 36394080, 2023).
infection (7 papers, 2014 to 2025). The state of being infected such as from the introduction of a foreign agent such as serum, vaccine, antigenic substance or organism. "Blocking VSIR or ISX with specific RNAi abolished SARS-2-S–induced inflammation and metabolic disturbances, underscoring the critical role of the VSIR–ISX axis in maintaining immune–metabolic balance during infection." (PMID 41417109, 2025).
neurodegenerative disease (3 papers, 2021 to 2025). A disorder of the central nervous system characterized by gradual and progressive loss of neural tissue and neurologic function. "Particularly, in the context of neurodegenerative disease, CCL2 and VSIR have been associated with microglial activation and neuroinflammation." (PMID 41279937, 2025).
VSIR also shares sentences with these, for which no sentence is quoted: melanoma (69 papers); prostate carcinoma (39); pancreatic cancer (36); colorectal cancer (27); glioma (21); colon carcinoma (19); hepatocellular carcinoma (19); endometrial cancer (17); lupus (16); non-small cell lung carcinoma (16); oral squamous cell carcinoma (14); psoriasis (12); COVID-19 (11); Sepsis (10); asthma (9); cervical carcinoma (9); esophageal adenocarcinoma (9); metastatic melanoma (9); pancreatic ductal adenocarcinoma (9); bladder cancer (8); cutaneous melanoma (8); glioblastoma (8); leukemia (7); rheumatoid arthritis (7); sarcoma (7); serous ovarian cancer (7); gestational trophoblastic neoplasia (6); lymph node metastasis (6); ovarian tumors (6); squamous cell carcinoma (6).
A further 136 diseases each share a sentence with VSIR in 5 papers or fewer.